TMED10P1 (transmembrane p24 trafficking protein 10 pseudogene 1)
Synonyms: Tmp21-II; formerly TMED10P
Gene: Processed pseudogene on chromosome 8 (144,994,886 to 144,995,540, forward strand). Ensembl gene ENSG00000254618.
Diseases named in the same sentence as TMED10P1 in open-access papers:
TMED10P1 is named in the same sentence as 2 diseases in open-access papers, as found by Europe PMC text mining. Sharing a sentence is not in itself a finding about the gene and the disease.
TMED10P1 shares sentences with these, for which no sentence is quoted: diabetes mellitus (1 paper); inflammatory bowel disease (1).